MCL1 (MCL1 apoptosis regulator, BCL2 family member)
Diseases named in the same sentence as MCL1 in open-access papers (continued):
Sharing a sentence is not in itself a finding about the gene and the disease.
triple-negative breast carcinoma (42 papers, 2014 to 2026). An invasive breast carcinoma which is negative for expression of estrogen receptor (ER), progesterone receptor (PR), and human epidermal growth factor receptor 2 (HER2). "Aberrant expression of myeloid cell leukemia-1 (MCL-1) is a major cause of drug resistance in triple-negative breast cancer (TNBC) cells." (PMID 27217294, 2016). "In summary, we have demonstrated some of the effects of CDK8 inhibition on CDK8, E2F1, STAT3, and Mcl-1 proteins in MDA-MB-468 triple-negative breast cancer cells." (PMID 41596544, 2026). "Another study using aptamers that knock down CD47 and MCL1 suggested additive immune-stimulating effects when combined in a mouse triple-negative breast cancer model." (PMID 36768931, 2023). "Antagonizing Myeloid cell leukemia 1 (MCL-1) in triple negative breast cancer (TNBC) can enhance the efficacy of SFK inhibitors." (PMID 31735913, 2020). "Evidence supporting the therapeutic targeting of MCL-1 was brought in the triple-negative breast cancer and HER2-amplified molecular subtypes." (PMID 30631150, 2019). "In triple negative breast cancers following neoadjuvant chemotherapy, MCL1 expression was amplified in 54% of the examined samples." (PMID 31404252, 2019). "In agreement with previous findings in triple negative breast cancer with BET PROTAC BETd-24615, BETd-260 rapidly caused complete depletion of Mcl-1 in OS cells." (PMID 31653826, 2019). "The clinical applicability of these findings was tested through a combination of approaches including knock-down or inhibition of MCL-1 to show triple-negative breast cancer cell line dependence on MCL-1 in vitro and in vivo." (PMID 29339815, 2018). "We next investigated the effects of MCL-1 antagonism on the ability of triple-negative breast cancer cells to disseminate to the lung, using cohorts of mice bearing MDA-MB-468-2A and MDA-MB-231-2A mammary intraductal xenografts." (PMID 27931239, 2016). "(C) Kaplan–Meier survival curves and log-rank p values of time to overall survival of patients with triple-negative breast cancer and with MCL-1 CNV alteration." (PMID 27931239, 2016). "Endogenous MCL-1:BIM complexes are also present in the responsive triple-negative breast cancer cell lines in this study." (PMID 27931239, 2016). "The data presented provide first evidence for the efficacy of MCL-1 inhibition for the suppression of metastasis in triple-negative breast cancer." (PMID 27931239, 2016). "To test this, we selected triple-negative breast cancer cell lines that differ with regard to their dependence on MCL1." (PMID 26910119, 2016). "The aim of our study was to investigate the functional role of both miR-101 and MCL-1 in the sensitivity of human triple-negative breast cancer (TNBC) to paclitaxel." (PMID 26036638, 2015). "Given the experimental evidence from our study, MIM1 – a selective Mcl-1 protein inhibitor- may be considered a potent apoptosis inducer in triple-negative breast cancer cells." (PMID 40892149, 2025). "In addition, S63845, a specific inhibitor of MCL-1, has shown promise in preclinical models of triple-negative breast cancer." (PMID 38316463, 2024). "Together, we found that NSC260594 might serve as a lead compound for triple-negative breast cancer therapy through targeting Mcl-1." (PMID 37481672, 2023). "In triple-negative breast cancer, MCL1 amplification correlates with poor prognosis." (PMID 32131385, 2020). "Interestingly, MCL-1 in cooperation with MYC induced drug resistance in triple-negative breast cancer via upregulation of mitochondrial oxidative phosphorylation and expansion of cancer stem cells." (PMID 33308268, 2020). "MCL-1 knockdown only affects the viability of a subset of triple-negative breast cancer cell lines." (PMID 28101374, 2017).
triple-negative breast carcinoma (continued). "Furthermore (as recently reported for MCL1 in the case of triple-negative breast cancer), predictive signatures should additionally take into account not only mRNA expression, but also protein levels of MARCH5 and BCL2 family members." (PMID 26910119, 2016). "MicroRNA-101 targets EZH2, MCL-1 and FOS to suppress proliferation, invasion and stem cell-like phenotype of aggressive endometrial cancer cells; MicroRNA-101 inhibits cell progression and increases paclitaxel sensitivity by suppressing MCL-1 expression in human triple-negative breast cancer." (PMID 32309578, 2016). "Importantly, targeting MCL-1 may provide an alternate treatment option for triple negative breast cancer patients in combination with Taxol." (PMID 36672454, 2023). "In this study, we have demonstrated that triple negative breast cancer cells depend on the presence of BCL-xL and MCL-1 for their survival, which aligns with prior research findings." (PMID 38898061, 2024). "For example, UMI-77 can antagonize MCL1 function by blocking the heterodimerization of MCL1/BAX and MCL1/BAK and exhibits tumor inhibitory activity in a triple-negative breast cancer cell xenograft mouse model." (PMID 34156978, 2021). "Molecular profiling of tumor cells persisting after neo-adjuvant chemotherapy for triple-negative breast cancer showed amplifications of MYC(54%) and MCL-1(35%)." (PMID 33308268, 2020). "This study provides the first in-vivo evidence to support the efficacy of MCL-1 BH3 mimetics in triple-negative breast cancer as single agents, and in combination with SRC family kinase inhibitors such as dasatinib." (PMID 27931239, 2016). "Finally, it has been shown in chemotherapy-resistant triple negative breast cancers that MYC and myeloid cell leukemia-1 (MCL1) genes are overexpressed, therefore promoting an OXPHOS metabolism." (PMID 33499022, 2021). "Recently, amplification of Mcl-1 gene loci was also found in triple-negative breast cancer, and NOXA, an endogenous Mcl-1 inhibitor, depressed HER2-positive breast cancers, suggesting that DRB could be further explored as treatment strategies for ER-negative breast cancer." (PMID 37537243, 2023). "In addition, our results pointed out that the inhibition of Mcl-1 and MITF activity could be considered a target in triple-negative breast cancer treatment." (PMID 36045272, 2022).
myeloid leukemia (35 papers, 2006 to 2025). A clonal proliferation of myeloid cells and their precursors in the bone marrow, peripheral blood, and spleen. "Myeloid cell leukemia 1 (MCL-1) was isolated from a human myeloid leukemia cell line and belongs to the Bcl-2 protein family." (PMID 39403382, 2024). "In line with this, herein, we utilized two myeloid leukemia cell lines to study the antileukemic efficacy of a novel MCL-1 inhibitor, S63845." (PMID 37108344, 2023). "Mcl-1, a member of the Bcl-2 anti-apoptotic protein subfamily, was first identified in the ML-1 human myeloid leukemia cell line in 1993." (PMID 35632731, 2022). "Other top-ranked genes include MCL-1 (related to Myeloid Leukemia), ACE2 (related to human coronavirus), SOD2 (related to idiopathic cardiomyopathy, premature aging, sporadic motor neuron disease, and cancer), and so on." (PMID 35571049, 2022). "Myeloid cell leukemia-1 (Mcl-1) was first identified in 1993 from a screen for genes induced by phorbol 12-myristate 13-acetate in a ML-1 human myeloid leukemia cell line." (PMID 34336857, 2021). "Myeloid cell leukemia 1 (MCL1) was discovered as a prosurvival gene expressed during phorbol ester-induced differentiation of ML-1 human myeloid leukemia cell line." (PMID 34576319, 2021). "MCL1 was initially identified as an immediate early gene expressed during PMA-induced differentiation of myeloid leukaemia cells." (PMID 31467488, 2019). "MCL1 was discovered by Ruth Craig and colleagues in 1993, which was originally identified as a gene up-regulated early in the differentiation of a human myeloid leukemia cell line." (PMID 29152113, 2017). "Mcl-1 is a Bcl-2 family protein and was originally identified as an early induction gene from human myeloid leukemia cell line ML-1." (PMID 29137317, 2017). "Pro-inflammatory stimuli caused strong, mainly transcriptional, A1 upregulation, in contrast to posttranscriptional regulation of Mcl-1 (induced myeloid leukemia cell differentiation protein)." (PMID 26890142, 2016). "The Mcl-1 gene was originally identified as being over-expressed in a human myeloid leukemia cell line during monocyte-to-macrophage differentiation." (PMID 24531335, 2014). "The purpose of this study is to analyze the expression pattern of miR-29a/29b and its target genes Mcl-1 (myeloid cell leukemia sequence 1) and B-cell lymphoma 2 (Bcl-2) in myeloid leukemia." (PMID 25006537, 2014). "Down-regulated miR-29a and miR-29b, and accompanying up-regulated Bcl-2 and Mcl-1 are the common feature in myeloid leukemias." (PMID 25006537, 2014). "In silico analysis of testis genes containing the consensus HRE (5’-RCGTG-3’) identified the induced myeloid leukemia cell differentiation (Mcl-1) gene as a potential HIF-1 target gene." (PMID 23216940, 2012). "Myeloid cell leukemia 1 (Mcl-1) is an antiapoptotic protein identified as an early gene induced during differentiation of ML-1 myeloid leukemia cells." (PMID 22570787, 2012). "Myeloid cell leukemia-1 (Mcl-1) is an anti-apoptotic member of the Bcl-2 family, originally identified as an early induction gene during differentiation of myeloid leukemia cells." (PMID 17014711, 2006). "Therefore, understanding the molecular regulatory network of MCL-1 is of tremendous importance to be able to control the survival-promoting MCL-1 function in myeloid leukemia." (PMID 34294680, 2021). "Myeloid cell leukemia-1 (MCL-1) is a pro-survival member of the Bcl-2 family that is initially identified as an immediate-early gene expressed during differentiation of ML-1 myeloid leukemia cells and is considered as an anti-apoptotic gene." (PMID 29344420, 2017). "Mcl-1 (Myeloid cell leukemia 1) is an anti-apoptotic member of the Bcl-2 family that was originally identified as an immediate early gene expressed during TPA-mediated differentiation of a human myeloid leukemia cell line." (PMID 24814761, 2014).
myeloid leukemia (continued). "For further understand the characteristic of expression and regulation of miR-29 in myeloid leukemia, we searched from miRWalk datebase and found two anti-apoptotic genes Mcl-1 and Bcl-2, which are target genes by both miR-29a and miR-29b and highly correlate to myeloid leukemia." (PMID 25006537, 2014). "Additionally, we propose that another possible target for testicular HIF-1 is the myeloid cell leukemia-1 (Mcl-1) gene, an antiapoptotic member of the Bcl-2 family, which was first discovered in the human ML-1 myeloid leukemia cell line." (PMID 23216940, 2012). "Mcl-1, a member of the anti-apoptotic Bcl-2 family, was originally cloned as an immediate-early induction gene expressed during differentiation of the ML-1 myeloid leukemia cells and functions as a regulator for survival and development in diverse cell types physiologically." (PMID 24947165, 2014). "Myeloid cell leukemia-1 (MCL-1), a member of the B-cell lymphoma-2 (BCL-2) protein family, was initially discovered during the differentiation of human myeloid leukemia cells into monocytes or macrophages with phorbol 12-myristate 13-acetate (TPA) exposure." (PMID 39012900, 2024). "Myeloid-cell leukemia 1 (MCL-1) was discovered, isolated (and named) from the human myeloid leukemia cell line ML-1." (PMID 33308268, 2020). "Consistent with recent studies, the inhibition of the PI3K/AKT pathway significantly induces antiapoptosis and promotes survival through Mcl-1 and Bcl-2 degradation in AML, human myeloid leukemia cells, and HCC." (PMID 30678274, 2019). "The human MCL-1 gene is located on chromosome 1q21, and MCL-1 proteins were originally isolated from myeloid leukemia cells." (PMID 25324720, 2014). "The fact that Mcl-1 has been reported to be the primary protein responsible for the resistance to ABT 737 in small cell lung cancer and myeloid leukaemia has also suggested that reduction in Mcl-1 would be an important cancer therapeutic target." (PMID 23387989, 2013). "It was shown that high MCL-1 expression and BCL-2 phosphorylation markedly reduced the ability of ABT-737 to induce apoptosis, whereas up-regulation of MCL-1 and BCL-XL was found to be responsible for the resistance of myeloid leukemia cell lines to ABT-199." (PMID 37108344, 2023). "The exact role of miR-125b is complicated by the fact that it is predicted to target more tumor suppressors than oncogenes, and one of the most important predicted candidates is the antiapoptotic MCL1 (Myeloid cell leukemia 1), a gene frequently upregulated in CLL and myeloid leukemias." (PMID 21461378, 2011).
chronic myeloid leukemia (33 papers, 2006 to 2026). "It has also been observed that triptolide inhibits JAK2 transcription by causing the fragmentation of Mcl1 by caspase-3, diminishing Bcl2 and Mcl1 levels in cells with chronic myeloid leukemia." (PMID 38293343, 2024). "HHT is a protein translation inhibitor and induces apoptosis in AML cells with Mcl-1 downregulation, and it is approved for treatment of chronic myeloid leukemia resistant to BCR-ABL inhibitors." (PMID 36739272, 2023). "For instance, the USP9X inhibitor WP1130 lowers Mcl-1 levels in chronic myelogenous leukemia and enhances sensitivity to apoptosis by facilitating Mcl-1 degradation." (PMID 35301297, 2022). "A significantly lower expression of miR-29b and a higher expression of the potential target gene Mcl-1 were found in peripheral blood mononuclear cells from acute and chronic myeloid leukemia patients compared with a group of healthy individuals." (PMID 29662889, 2018). "Mcl-1 is required for proliferation and survival of hematopoietic stem cells and is a transcriptional target of Gfi1 in chronic myelogenous leukemia." (PMID 30286780, 2018). "The USP9X inhibitor WP1130 lowers MCL-1 levels in chronic myelogenous leukemia and enhances sensitivity to apoptosis by facilitating MCL-1 degradation." (PMID 28659182, 2017). "Similarly, SPHK1 inhibition reduce BCR/ABL-induced upregulation of MCL-1 in chronic myeloid leukemia cells." (PMID 37020867, 2023). "Besides, HULC regulated the miR-150-5p/MCL1 axis to enhance imatinib resistance in chronic myeloid leukemia." (PMID 34250246, 2021). "Similarly, downregulation of miR-181 was responsible for resistance to imatinib by directly targeting the Bcl-2 family member Mcl-1 in chronic myelogenous leukemia cells." (PMID 25871397, 2015). "Similarly, overexpression of Sphk1 inhibits the activation of caspase 3, cytochrome c and SMAC/Diablo release from mitochondria through the modulation of Bim, Bcl‐XL and Mcl1 in chronic myeloid leukaemia cells." (PMID 25056275, 2015). "Thus, down-regulation of Mcl-1 triggered by Roscovitine analogues would suppress the survival advantage conferred by Mcl-1 in chronic myeloid leukemia, resulting in apoptotic cell death." (PMID 26184865, 2015). "HHT induces AML cell apoptosis via Mcl-1 downregulation and is an FDA-approved treatment for clinical chronic myeloid leukaemia." (PMID 38658865, 2024). "Among these genes, MTOR, STAT3, MCL1, LAMC1, and KRAS have been reported to play roles in imatinib resistance in chronic myeloid leukemia in parallel with our findings." (PMID 38916832, 2024). "In hematological malignancies, increased levels of MCL-1 have been described in multiple myeloma (MM), DLBCL, AML, chronic myeloid leukemia (CML) and mantle cell lymphoma (MCL)." (PMID 32131385, 2020). "In chronic myelogenous leukemia (CML), overexpression of tyrosine-protein kinase, Lyn, has been shown to reduce miR-181 expression, which directly targets MCL1." (PMID 29361709, 2018). "The reduced USP9X and MCL1 levels were recently found to block BCR-ABL kinase signaling, taking chronic myelogenous leukemia cells to apoptosis." (PMID 22016818, 2011). "Initially, we tested protein synthesis and MCL-1 non-specific inhibitor homoharringtonine, with the benefit of its clinical use to treat chronic myeloid leukemia with only minor side effects." (PMID 35951353, 2022).
B-cell lymphoma (30 papers, 2012 to 2026). "Knockdown of USP9X leads to suppressed lymphoma growth and increased sensitivity to chemotherapy by destabilizing X-linked inhibitor of apoptosis protein (XIAP) in B-cell lymphoma, independently of Mcl-1." (PMID 34454635, 2021). "In diffuse large B cell lymphoma (DLBCL) and follicular lymphoma (FL), USP9X deubiquitinates Mcl-1 and protects it from degrading, while high-level Mcl-1 is associated with malignant B-cell proliferation and poor outcomes in B-cell lymphoma patients." (PMID 34454635, 2021). "On the contrary, overexpression of BCL-XL and MYC caused B-cell lymphoma, and overexpressed MCL-1 accelerated MYC-driven B-cell lymphoma development." (PMID 32575557, 2020). "Furthermore, MCL-1 copy number gains and mutations are often found in B cell lymphomas." (PMID 28425914, 2017). "MCL1 is needed throughout B-cell development and is often deregulated in B-cell lymphomas with a GC origin." (PMID 37474714, 2023). "Upregulation of MCL1 expression suggests tumorigenesis, with greater than 85% of MCL1 transgenic mice developing B-cell lymphoma within two years." (PMID 36984512, 2023). "Our results indicate a synergistic effect of dinaciclib‐based combinations with B‐cell lymphoma 2 or B‐cell lymphoma extra‐large inhibitors, especially in MM cell lines with partial dependence on myeloid cell leukemia sequence 1 (MCL‐1)." (PMID 37704591, 2023). "Screening of a large tumor cell line panel comprising 952 cancer cell lines, across different malignancies for their sensitivity to a precursor of AMG-176 (AM-8621), identified B-cell lymphoma as most dependent on MCL-1, next to MM." (PMID 33308268, 2020). "The mechanismof MCL-1 induced survival and transformation in the genome, theMCL-1-overexpressing B-cell lymphoma." (PMID 31285648, 2019). "The importance of the miR-181 target Mcl-1 in CLL survival was demonstrated by rapid apoptosis of CLL cells following siRNA-mediated down-regulation of Mcl-1, and by the Mcl-1 transgenic mice, which developed B-cell lymphoma." (PMID 23431463, 2013). "Because numerous genes located on chromosome 1q21 are linked to B-cell lymphoma, including BCL9, MCL1, and IRTA1, a gene on chromosome 1q21 in this patient might be dysregulated due to the IGL translocation." (PMID 40729218, 2025). "An ABT-737-induced reduction in maximal O2 consumption was also detectable in SP53, JeKo-1, and WEHI-231 B-cell lymphoma cell lines, with sensitivity correlating with BCL-2:MCL-1 ratio and with susceptibility (SP53 and JeKo-1) or resistance (WEHI-231) to ABT-737-induced apoptosis." (PMID 22880001, 2012). "Hence, the down-regulation of BCL-XL and MCL-1 could be beneficial for treating B-cell lymphoma, including DLBCL." (PMID 32575557, 2020). "Early clinical data as well as preclinical data indicate that also in mantle cell lymphoma, which is largely characterized by high expression of BCL-2 and showed a more promising clinical response to venetoclax than other subtypes of B-cell lymphoma, MCL-1 may be a valuable therapeutic target." (PMID 33308268, 2020). "In addition to functional inhibitors, alternative strategies to counteract MCL-1 resistance have been explored, such as downregulation of MCL-1 expression by caloric restriction in B-cell lymphoma or by cardiac glycoside UNBS1450 in AML." (PMID 29570632, 2018).